KRAS (KRas proto-oncogene, GTPase)
Diseases named in the same sentence as KRAS in open-access papers (continued):
Sharing a sentence is not in itself a finding about the gene and the disease.
pancreatic cancer (continued). "CCAT2, the lncRNA that promotes colorectal cancer growth, metastasis, and chromosomal instability upregulates WNT and CMYC signaling when activated by the WNT pathway, but also by the KRAS-MEK axis in pancreatic cancer." (PMID 32545208, 2020). "The RPE enzyme belongs to the nonoxidative arm of the PPP, and its expression is regulated by KRAS in pancreatic cancers (PDAC)." (PMID 32365991, 2020). "Glutamate-mediated AMPAR activation was found to increase invasion and migration of pancreatic cancer cells by activating KRAS-MAPK signaling pathway." (PMID 33117704, 2020). "This pathway in pancreatic cancer cells is primarily dominated by mutant KRAS, which results in GDH repression and GOT1 promotion." (PMID 32122374, 2020). "Pancreatic tumor 3D clusters recapitulated mutant KRAS dependency and recalcitrance to MEK inhibition." (PMID 32636409, 2020). "Pancreatic cancer was one of the first malignant diseases, in which specific single nucleotide variants (SNV) mutations in the KRAS (Kirsten rat sarcoma viral oncogene homolog) gene were detected in cfDNA." (PMID 33147766, 2020). "In this work we have examined the role of PARP-1 in the activation of the transcription of KRAS in pancreatic cancer cells." (PMID 32872305, 2020). "To test this, we performed RNA-seq and genome-wide DNA methylation analysis using Illumina’s Infinium arrays to determine the effect of silencing of KRAS in the 11 KRAS-mutant and -dependent pancreatic cancer cells." (PMID 32576853, 2020). "Our findings argue for exploring the therapeutic index of the MEKi/CD40 Ab combination in mutant KRAS-driven tumors such as pancreatic cancer." (PMID 32358491, 2020). "Nevertheless, the authors also demonstrated that DRP1 deletion in pancreatic cancer cells conferred a significant survival advantage in a model of KRas-driven tumor." (PMID 33233365, 2020). "Morever, dysregulation of the PINK1/PARK2 axis accelerates KRAS-mediated carcinogenesis in pancreatic cancer." (PMID 33139776, 2020). "The balance between EVI1 and miR-96 and the EVI1/miR-96/KRAS axis appears to play an important role in regulating the growth of pancreatic tumor cells." (PMID 32752071, 2020). "Studies were predominantly retrospective cohort studies, where the diagnosis of pancreatic cancer was known in a total of 850 patients at the time of mutant KRAS testing, equating to a pancreatic cancer prevalence of 39%." (PMID 32825312, 2020).
pancreatic cancer (continued). "We first performed genome-wide DNA methylation profiling of 11 KRAS-dependent pancreatic cancer cell lines using the Infinium HumanMethylation450 BeadChip Array31." (PMID 32576853, 2020). "In the dPCR assay, KRAS G12/G13 mutations were found in the PDA from 10 patients, including IPMN-associated pancreatic cancers; 1 PDA patient exhibited mutant KRAS Q61H." (PMID 32704002, 2020). "Recently, a study indicated that increased fatty acid oxidation (FAO) induced by REDD1 deficiency generates NADPH and GSH, which results in decreased oxidative stress and drives KRAS mutant pancreatic cancer progression." (PMID 33117704, 2020). "The clinical-grade iExosomes were tested in multiple in vitro and in vivo studies to confirm suppression of oncogenic KRAS and an increase in the survival of several mouse models with pancreatic cancer." (PMID 32974169, 2020). "GSK-3 activity is required for the growth of certain mutant KRAS-driven tumors including pancreatic cancers such as MIA-PaCa-2 cells." (PMID 32365809, 2020). "We compared the panel of 11 KRAS-mutant pancreatic cancer cell lines to DNA methylation data collected from SALEB and SAKRAS lung epithelial cells and published Infinium methylation data from ENCODE32." (PMID 32576853, 2020). "Ω-3 enriched diet with fish oil prevented pancreatic carcinoma in KRAS mice via AKT pathway inhibition." (PMID 32526973, 2020). "Oncogenic KRAS is a master regulator of pancreatic cancer metabolism, and mutant Kras copy number can define metabolic reprogramming and therapeutic susceptibilities." (PMID 30819189, 2019). "Our data indicate that LIF is stimulated by KRAS and further it plays an important role in facilitating KRAS to drive pancreatic cancer." (PMID 31296870, 2019). "Farnesyl transferase inhibitors were ineffective in phase II and III clinical trials for the treatment of pancreatic cancer due to alternative KRAS prenylation by geranylgeranyl transferases." (PMID 31878223, 2019). "Taken together, PAI-1 is a potential downstream target of the KRAS/ERK pathway in pancreatic cancer cells." (PMID 31695760, 2019). "It has been reported that EGFR is required for KRAS-induced pancreatic tumorigenesis and therefore served as a therapeutic target for pancreatic cancer." (PMID 31514441, 2019). "In line with this, preliminary unpublished work in our laboratory has shown that attenuation of SEMA3C signalling dampens cell proliferation and oncogenic cell signalling in panel of KRAS mutant pancreatic cancer cell lines." (PMID 30759745, 2019). "On the protein level, we noticed marked upregulation of KRAS protein expression level in most of pancreatic cancer cells in comparison to normal pancreatic cells." (PMID 30654191, 2019). "KRAS, which is considered as undruggable, has been demonstrated by several groups to be able to modulate the immune response, as in colorectal and pancreatic cancers." (PMID 31405063, 2019). "In fact, our data confirmed that the chimeric RC‐ODC fusion protein molecule downregulated the level of the KRAS oncoprotein after co‐transfection with AZ and inhibited the growth of the pancreatic cancer cell line PANC‐1 in vitro and in vivo." (PMID 30347501, 2019).
pancreatic cancer (continued). "In KRAS-driven pancreatic cancer models, deletion of LKB1 enhanced the tumorigenicity and proliferation rate of cancer cells through enhanced serine biosynthesis and S-adenosyl-methionine (SAM), which supports DNA methylation." (PMID 31681559, 2019). "Our study showed for the first time that detection of KRAS ctDNA levels within a short period enables the prediction of prognosis and therapeutic responses in patients with pancreatic cancer." (PMID 31891652, 2019). "These demonstrate that LODER-derived siG12D significantly suppresses pancreatic cancer growth, both in vitro and in vivo, and impedes pancreatic tumor growth, although all of the past studies with direct KRAS modifications for pancreatic cancer had failed." (PMID 31284594, 2019). "In line with this, another independent study using short hairpin (sh) RNA screen had similar findings in KRAS-mutant lung and pancreatic cancer cells." (PMID 31612108, 2019). "We further demonstrate that this system can deliver siRNA to the tumor microenvironment, reduce KRAS expression, and inhibit pancreatic cancer growth in vivo." (PMID 31413817, 2019). "Previous studies have demonstrated the induction of YAP activity upon loss of the tumor suppressor APC in colon cancer, or as a mechanism to bypass oncogenic KRAS addiction in pancreatic cancer cells." (PMID 30717152, 2019). "When KRAS was silenced, RAD51 expression decreased in pancreatic cancer cells lines that harbor KRAS mutation." (PMID 31889908, 2019). "Coincidently, our previous results demonstrated that hypoxia-induced lncRNA-NUTF2P3-001 acts as competitive endogenous RNA (ceRNA) to depress the inhibition of miR-3923 on KRAS, which contributes to tumorigenesis of pancreatic cancer." (PMID 31367258, 2019). "Recent work by the Rosenberg group revealed KRASmut-specific CD4+ T-cells, and KRAS-specific tumor-infiltrating IgG B-cells were identified in patients with pancreatic cancer." (PMID 31665076, 2019). "In this report, we provide evidence that RAD51, regulated by KRAS, promotes pancreatic cancer cell proliferation." (PMID 31889908, 2019). "Accordingly, mutant KRAS-expressing pancreatic cancers utilize and rely on an alternative pathway to synthesize NADPH." (PMID 31288436, 2019). "Our results suggest that, even though IL-6 and LIF share STAT3 as a downstream effector, they have distinct functional roles in human pancreatic cancer cells harboring mutant KRAS." (PMID 31296870, 2019). "KRAS mutations are the most common alterations in IPMN of the pancreas and are considered as an early event of pancreatic cancer development." (PMID 31338331, 2019). "Our data suggest a crucial role of LIF in KRAS-driven pancreatic cancer and that blockade of LIF by neutralizing antibodies represents an attractive approach to improving therapeutic outcomes." (PMID 31296870, 2019). "Implantation of Local Drug EluterR (LODER), can release siRNAs targeting KRAS over months in pancreatic cancer in vivo." (PMID 31470511, 2019). "For instance, mutant KRAS in pancreatic cancer has been shown to activate glycolytic and hexosamine biosynthesis and a non-oxidative branch of the pentose phosphate pathways." (PMID 31416205, 2019). "Together, our analysis supports emerging evidence for rare recurrent and potentially therapeutically actionable RAF1 rearrangements in KRAS wild-type pancreatic cancer." (PMID 31097696, 2019). "For instance, KRAS is well known as the dominant oncogene in pancreatic cancer and its prevalence is generally over 90%." (PMID 31801585, 2019). "An ATG7-RAF1 rearrangement was previously reported in another KRAS wild-type pancreatic cancer model." (PMID 31097696, 2019).
pancreatic cancer (continued). "Third, inhibiting PI4KIIIα also reduced PtdSer and KRAS PM levels sufficiently to selectively abrogate the growth of KRAS-dependent pancreatic cancer cells." (PMID 31451509, 2019). "Exosomal delivery of siRNAs targeting KRAS reduced expression of KRAS, suppressed tumor formation, and inhibited metastatic progression in mouse pancreatic cancer models." (PMID 31681559, 2019). "Ectopic expression of miR-193b inhibits anchorage-independent growth by targeting ErbB4 in Ewing sarcoma and impairs the proliferation of pancreatic cancer cells through suppression of KRAS." (PMID 31262974, 2019). "KRAS-induced pancreatic cancers depend on the ME1-mediated NADPH generation to maintain redox balance and proliferation." (PMID 31288436, 2019). "This study showed that KRAS activation leads to the formation of invasive pancreatic cancer with a similar aggressive behavior as human pancreatic cancer, including the propensity to metastasize." (PMID 31861620, 2019). "The oncogene KRAS not only promotes the tumorigenesis of pancreatic cancers but also is required for the malignant progression and metastasis of these cancers." (PMID 30347501, 2019). "Specifically, mutant KRAS pancreatic cancer cells contain a CD133+/Mitohigh subpopulation of cells resistant to KRAS ablation that also exhibit enhanced mitochondrial metabolism and augmented OXPHOS dependency." (PMID 30413783, 2019). "In this study, we examined the correlation between RAD51 and KRAS mutation and the impact of RAD51 on cell proliferation and glucose metabolism reprogramming in pancreatic cancer." (PMID 31889908, 2019). "This radiosensitisation effect is even seen in KRAS-mutant pancreatic cell lines, which is highly relevant in clinical practice as > 90% of pancreatic tumours are KRAS-mutant." (PMID 30717707, 2019). "Increased levels of YAP-1 and Epidermal Growth Factor Receptor (EGFR) activation have been previously reported to be compensatory mechanisms to KRAS inhibition in pancreatic cancer cells." (PMID 31451509, 2019). "Activation of the MEK/ERK signaling pathway by the oncogenic KRAS G12D mutation increases secretion of IL-10 and TGF-β from pancreatic cancer cells, which promotes conversion of T-cells to an immunosuppressive regulatory T-cell (Treg) state." (PMID 31681559, 2019). "In particular, Let-7b miRNA have been shown to repress KRAS expression and inhibit mutant KRAS-dependent cell growth in vitro and tumor growth in vivo in lung and pancreatic cancer cell models." (PMID 29534749, 2018). "Oncogenic KRAS is nearly ubiquitously expressed in pancreatic cancers and these cancers are particularly dependent on MAPK pathway signaling." (PMID 29359686, 2018). "The tumour indications with the most frequent over-editing were ovarian cancer, melanoma and breast cancer showing a prevalence comparable to frequent neoantigen epitopes like KRAS G12D which is present in 33% of all pancreatic cancer patients." (PMID 30254248, 2018). "There has been renewed interest in exploring the small subset population of KRAS wild type pancreatic cancer patients." (PMID 29382159, 2018).
pancreatic cancer (continued). "To account for this prediction, we first investigated the cellular effects of Spiclomazine on activated KRasG12C (MIA PaCa-2), KRasG12V (CFPAC-1), and wild-type KRas (BxPC-3) pancreatic cancer cell lines by monitoring the active KRas-GTP level." (PMID 29467941, 2018). "For example, pancreatic cancers and melanoma cell lines, which have aberrantly active MEK signaling due to oncogenic KRAS and BRAF mutations, were modeled and are predicted to be the most responsive." (PMID 30323222, 2018). "First, we investigated the effects of BRAF and/or MEK inhibition (using dabrafenib and trametinib, respectively) on MAPK pathway activation in KRAS-mut lung and pancreatic cancer cell lines." (PMID 29986755, 2018). "Pancreatic cancer, in particular PDAC, is hallmarked by commonly mutated genes such as KRAS, one of the most well-known being a constitutively active mutant form, KRASG12D." (PMID 29710783, 2018). "FOSL1 was recently identified as a novel downstream effector of KRAS and higher FOSL1 expression was associated with poor survival outcome in both lung and pancreatic cancer patients." (PMID 30517129, 2018). "A similar model for SMYD2 has revealed that this enzyme also plays a role in KRAS driven pancreatic cancer initiation and progression and is important for the cellular response to genotoxic agents (e.g. gemcitabine)." (PMID 29856759, 2018). "We show here that Spiclomazine leads to an effective suppression in Ras-mediated signaling through abrogating the KRas-GTP level in the KRas-driven pancreatic cancer." (PMID 29467941, 2018). "Therapeutics against genes like KRAS and downstream effectors have shown little success, and this may be explained in part by the presence of other mutations and the recent discoveries regarding the involvement of epigenetics in pancreatic cancer development and progression." (PMID 29710783, 2018). "This study randomized 196 patients with KRAS wild type locally advanced or metastatic pancreatic cancer to 1 of 2 arms." (PMID 29382159, 2018). "This reprogramming of glutamine metabolism was driven by KRAS, one of the most common genetic alterations in pancreatic cancer." (PMID 29751795, 2018). "In this study, we established the first KRAS-initiated pancreatic cancer model that closely recapitulates human PanIN." (PMID 30533257, 2018). "As assessed by IP/WB, both RAF inhibitors caused BRAF/CRAF heterodimer formation in A549 cells; similar results were obtained in the KRAS-mut pancreatic cancer cell line HPAFII." (PMID 29986755, 2018). "Another recent study from our laboratory showed that oncogenic KRAS can be targeted directly and specifically in pancreatic cancer cells using exosomes loaded with short interfering RNA, which had previously been very difficult to achieve." (PMID 29580275, 2018). "PDCs were established from metastatic lesions of KRAS G12 V mutant pancreatic cancer patient (PDC#1) and KRAS wild type patient (PDC#2), respectively, as described in the Material and methods section." (PMID 30419860, 2018). "S100A10 was found to be highly overexpressed in pancreatic tumors, regulated the fundamental process of cellular invasion, regulated by KRAS signaling and DNA methylation, and contributed to tumor growth." (PMID 30009399, 2018). "More importantly, in vivo studies of SMYD3 knockout mice suggest that the enzyme is involved in KRAS driven lung and pancreatic cancer development and in the early stages of liver and colon carcinogenesis." (PMID 29856759, 2018). "In summary, we successfully developed a novel system combining CRE/Lox technology with the GAL4/UAS system to establish an oncogenic KRAS-initiated pancreatic cancer model." (PMID 30533257, 2018). "Pancreatic cancer metabolism is dramatically rewired by oncogenic KRAS that induces a series of metabolic alterations, which includes enhanced glycolysis and glutaminolysis, resulting in enhanced cell growth and proliferation." (PMID 29467405, 2018).